SPI1 (Spi-1 proto-oncogene)
Diseases named in the same sentence as SPI1 in open-access papers (continued):
Sharing a sentence is not in itself a finding about the gene and the disease.
COVID-19 (15 papers, 2020 to 2024). A disease caused by infection with severe acute respiratory syndrome coronavirus 2. "Determination of the putative TFs involved in the regulation of the DEGs implicated in COVID-19 and DM showed that SPI1 and RELA are involved in the expression of commonly upregulated genes in COVID-19, T1D and T2D." (PMID 34260684, 2021). "The overexpression of SPI1 and its targets suggests that this transcription factor may be involved in COVID-19 pathogenesis or susceptibility." (PMID 38262689, 2024). "In this work, the increased expression of SPI1 and its target was explicitly observed in patients with severe COVID-19, indicating that SPI1 has a vital role in transcriptional regulation during COVID-19." (PMID 38262689, 2024). "This work identified specific overexpressed genes related to neutrophils only in severe COVID-19 patients, such as SPI1, SLPI, S100A9, and BRI3, which indicates a specific expression regulation that occurs only in SARS-CoV-2 infection." (PMID 38262689, 2024). "The iRegulon analysis indicates that the ETS family of transcription factors, led by SPI1, were the regulators with the most enriched binding motifs between the up-regulated genes in severe COVID-19 patients (NES = 4.93) with 70 targets." (PMID 38262689, 2024). "Among these TFs, we observed strong up-regulation for SPI1 mRNA in monocytes in severe COVID-19 compared to healthy controls (pseudobulk DE and GEDI cluster-free DE analyses), but not for the other two TFs." (PMID 39097589, 2024). "It has been observed that transcription factors like SPI1, which is related to granule–progenitor differentiation, were up-regulated in COVID-19 patients." (PMID 38262689, 2024). "In contrast, our integrated analysis involved multiple datasets, enabling us to identify the specific up-regulation of SPI1 in severe COVID-19 cases." (PMID 38262689, 2024). "Protein SPI1 is the essential transcription factor used to predict dysregulated hematopoiesis in bone marrow in severe COVID-19 patients." (PMID 37877121, 2023). "The two main TFs that regulate the shared DEGs between COVID-19 and DM are ‘SPI1’ and ‘RELA’." (PMID 34260684, 2021). "In addition, we conducted score analysis to examine the transcriptional level of TF-downstream target genes, and identified substantial increase in scores of ETS2, FLI1, and SPI1 in COVID-19 patients compared with controls." (PMID 34349096, 2021). "Seven common key genes were found in these four hub gene sets, including FCER1G, ITGAM, LCP2, LILRB2, MNDA, SPI1, and TYROBP, which were considered core targets of IC and COVID-19." (PMID 38267482, 2024). "In contrast, SPI1 and RAB1B showed increased expression in three datasets of severe COVID-19 patients." (PMID 38262689, 2024). "We prioritized 4 out of 5 microglia PFC TFs (IRF8, ATF5, SPI1, TAL1) based on the upregulation in their activity in patients with COVID-19 (Z > 2.5, P < 0.05 and FDR within cell type < 0.05)." (PMID 34281603, 2021). "Collectively, MkP- and GP-priming TFs, including ETS2, FLI1, SPI1, and GATA2 were activated in the HSC/MPP cells from COVID-19 patients, probably contributing to the increased output of myeloid progenitor cells and decreased output of lymphoid progenitors." (PMID 34349096, 2021). "Consistently, the regulons including GATA2, SPI1, ETS2, FLI1, and ETV6 were activated in COVID-19 patients." (PMID 34349096, 2021).
COVID-19 (continued). "In addition, SPI1 and other ETS family transcription factors are the predicted regulators with the most enriched binding motifs between the overexpressed genes in severe COVID-19 patients." (PMID 38262689, 2024).
atherosclerosis (14 papers, 2015 to 2026). A disease characterized by the build-up of fatty material and calcium deposition in the arterial wall resulting in partial or complete occlusion of the arterial lumen. "By combining these results, the high reliability of expression of 1 TF (SPI1) in atherosclerosis and AAA was confirmed." (PMID 39560590, 2024). "Meanwhile, SPI1 was also predicted to be a vital TF in patients with RA complicated with atherosclerosis." (PMID 35304503, 2022). "A bioinformatic analysis and machine learning algorithms approach illustrated that 5 hub genes (SPI1, MMP9, C1QA, CX3CR1, MNDA) could predict the risk of atherosclerosis in SLE." (PMID 40725777, 2025). "This is consistent with our observation of the significant increase of SPI1 expression in Tibetan minipigs induced by the HFC diet, further suggesting that the activation of myeloid cells plays a very important role in the formation of atherosclerosis." (PMID 32213192, 2020).
colitis (14 papers, 2008 to 2026). Inflammation of the colon. "Oral infection of mice with Salmonella Typhimurium after streptomycin pretreatment causes substantial inflammation and colitis, which depends on the function of SPI1 and SPI2-encoded type three secretion systems." (PMID 32834002, 2020). "For S. Typhimurium, the type-3 secretion systems (T3SS) encoded by the SPI-1 and SPI-2 pathogenicity islands are important for inducing colitis during gut infection." (PMID 32834002, 2020). "To investigate the role of SPI-1 in the pathogenesis of colitis and diarrhea we infected BALB/c.D2Nramp1 mice with an invA mutant of 14028s, which has no functional SPI-1 secretion system and so cannot invade epithelial cells in vitro." (PMID 18270590, 2008). "We distinguish Salmonella-specific findings (e.g., SCFA suppression of SPI-1) from general colitis data and prioritize molecular validation, temporal mapping, multi-omics responder stratification, and standardized postbiotic development for clinical translation." (PMID 41683721, 2026). "Another study reported that a S. Typhimurium strain with disrupted SPI-1 was not completely attenuated, causing delayed colitis that became obvious at days 3 and 4 following infection." (PMID 37325511, 2023). "Since macAB was shown to play a role in the streptomycin pre-treatment model of colitis, we suspected that 4/74 could be using SPI-1 and/or SPI-2-induced inflammation in the gut to outcompete D23580." (PMID 32834002, 2020). "Rollenhagen and Bumann showed that SPI-1 genes are transcribed in the colon of mice with colitis." (PMID 18270590, 2008). "Moreover, DHA significantly decreased the protein expression levels of PU.1 (Spi-1 proto-oncogene) and AHR (Aryl hydrocarbon receptor) in the LPMCs of the OXA colitis model and decreased the protein levels of T-bet and RORγt in the TNBS colitis model." (PMID 31284478, 2019). "Most importantly, they showed that SPI-1 mutants of S. Typhimurium (invJ and invG ) did not produce colitis, though they still could infect the cecum as well as wild type (WT) Salmonella, and they were also invasive as measured by CFU in the mesenteric lymph nodes." (PMID 18270590, 2008).
glioma (14 papers, 2020 to 2025). A benign or malignant brain and spinal cord tumor that arises from glial cells (astrocytes, oligodendrocytes, ependymal cells). "For example, SPI1 is known to promote glioma cell proliferation and is associated with mesenchymal glioma stem cells, which exhibit the most malignant behavior." (PMID 41007824, 2025). "Furthermore, SPI1 can be utilized as a potential diagnostic marker and therapeutic target for glioma." (PMID 35361282, 2022). "SPI1 was reported overexpressed in glioma and could be utilized as a potential diagnostic marker and therapeutic target for glioma." (PMID 35945192, 2022). "SPI1 has been identified to facilitate the progression of multiple malignant cancers, such as melanoma, lung cancer, glioma 8 and other types of neoplasia." (PMID 39062086, 2024). "Among these TFs, CTCF, POLR2A, SIN3A, and SPI1 concurrently regulated all five prognostic genes in glioma." (PMID 39491527, 2024). "SPI1 has been reported to be related to the progression of glioma, cervical cancer, breast cancer, and so on." (PMID 36967718, 2023). "In order to investigate the role of SPI1 in glioma tumorigenesis, we determined the expression of SPI1 in 10 paired glioblastoma (GBM) tissues and adjacent normal counterparts by qRT-PCR." (PMID 35361282, 2022). "Double luciferase activity and chromatin immunoprecipitation assay results indicated that SPI1 can bind to the promoter sites and promote the proliferation and migration of glioma cells by regulating the expression of oncogenic PAICS." (PMID 35361282, 2022). "Although SPI1 is an oncogene in glioma and GBM, the exact cancer-promoting mechanism and signaling of SPI1 are not clear." (PMID 35945192, 2022). "Our goal was to explore the role of SPI1 in the occurrence and development of glioma with regards to regulation of PAICS, and provide a new direction for further exploration of glioma pathogenesis." (PMID 35361282, 2022). "In order to understand SPI1 functionality in glioma progression, we knocked down PAICS expression with siRNAs in the U87 and U251 cells, respectively." (PMID 35361282, 2022). "Flow cytometry revealed that knock down in the expression of SPI1 in U87 and U251 cells increased the proportion of cells in G0/G1 phase, and they decreased the proportion of glioma cells in the S phase." (PMID 35361282, 2022). "We observed that the expression level of SPI1 was up-regulated in glioma tissues, compared to normal tissues." (PMID 35361282, 2022). "In glioma, results have shown that SPI1 plays a cancer-promoting role, but the functional verification and mechanism of SPI1 have not yet been reported." (PMID 35361282, 2022). "The results demonstrated that PAICS was able to reverse the decrease in proliferation and migration of glioma cells induced by SPI1 interference." (PMID 35361282, 2022). "Through the rescue experiment, we also validated that SPI1 can promote proliferation and migration of tumor cells in glioma through PAICS." (PMID 35361282, 2022). "By analyzing the glioma data in the TCGA database, the expression level of SPI1 displayed a significant positive correlation with target genes (CX3CR1: r = 0.53; CSF1R: r = 0.876; IRF8: r = 0.678)." (PMID 34434898, 2021). "In this study, we investigated expression, function and mechanism of SPI1 in glioma." (PMID 35361282, 2022). "Furthermore, we found that SPI1 is able to promote proliferation and migration of glioma cells in vitro." (PMID 35361282, 2022). "SPI1 expression in glioma was identified using qRT-PCR and Western blotting." (PMID 35361282, 2022). "Our results suggest that SPI1 can promote proliferation and migration of glioma." (PMID 35361282, 2022). "The mechanism of how SPI1 promotes glioma progression remains uncertain." (PMID 35361282, 2022). "SPI1 expression is upregulated in glioma and is involved in the progression of glioma." (PMID 36117773, 2022). "Although SPI1 was reported to promote glioma progression, the exact mechanism was still unclear." (PMID 35945192, 2022).
glioma (continued). "Furthermore, we discovered that a decrease in the expression of SPI1 increased the apoptotic rate of glioma cells." (PMID 35361282, 2022). "Therefore, the results demonstrated that SPI1 exerts an oncogenic effect to promote cell growth and migration in glioma." (PMID 35361282, 2022). "The role of SPI1 in the development of glioma is related to regulation of PAICS." (PMID 35361282, 2022). "Compared to the normal group, the SPI1 mRNA and protein are up-regulated in glioma tissues." (PMID 35361282, 2022). "The purpose of this study was to investigate the role of the transcription factor SPI1 in glioma." (PMID 35361282, 2022). "Our results indicate that SPI1 may be a promising target for the treatment of glioma." (PMID 35361282, 2022). "Moreover, we discovered that suppression of SPI1 decreases glioma cell growth and migration." (PMID 35361282, 2022). "To date, no studies have reported on the relationship between SPI1 Phosphoribosylaminoimidazole Carboxylase and Phosphoribosylaminoimidazolesuccinocarboxamide Synthase (PAICS) in glioma." (PMID 35361282, 2022).
myeloid leukemia (14 papers, 2011 to 2025). A clonal proliferation of myeloid cells and their precursors in the bone marrow, peripheral blood, and spleen. "SPI1, according to its higher activity in myeloid PBMCs, was more essential in myeloid leukemias (Wilcoxon-test p value = 0.038)." (PMID 32051003, 2020).
Sepsis (14 papers, 2017 to 2025). Sepsis is defined as life-threatening organ dysfunction caused by a dysregulated host response to infection. "For instance, it was reported that the mutation of the Spi1 gene, which encodes the PU.1 transcription factor specific to hematopoietic lineages, affects lymphoid development and causes septicemia and death at birth." (PMID 34386488, 2021). "Bioinformatics analysis underscored the pivotal role of activated hemocytes in diagnosing pediatric sepsis, with SPI1, TYROBP, and FCER1G co‐expression influencing the disease's pathophysiology by modulating neutrophil and platelet activity." (PMID 40626122, 2024). "Notably, for the first time, SPI1‐TYROBP‐FCER1G co‐expression has been found to contribute to the pathophysiology of pediatric sepsis through influencing the activity of neutrophils and platelets." (PMID 40626122, 2024). "Notably, elevated expression levels of SPI1, TYROBP, and FCER1G were observed in pediatric sepsis or septic shock, with positive correlations between SPI1, FCER1G, and TYROBP." (PMID 40626122, 2024). "While Spi1−/− mortality at P0 probably results from multiple functional defaults that are not necessarily exclusively CNS related, the cause of death is very unlikely related to an immune system deficiency or the development of septicemia that could have arisen due to the absence of microglia." (PMID 36321865, 2022). "This network uncovered regulatory interactions among genes like MPO, CXCR2, ITGAM, SPI1, SPI1 and EP300, suggesting these TFs may participate in sepsis-related immune responses and inflammatory regulation by modulating the transcriptional activity of core genes." (PMID 41259376, 2025). "However, the role of the SPI1‐TYROBP‐FCER1G network in pediatric sepsis has not been previously reported." (PMID 40626122, 2024). "In sepsis, RELA, CEBPB, NFKBIA, STAT6, IRF8 and SPI1 were downregulated, with no significant change in NFKB1, JUN and GLI1." (PMID 39444551, 2024).
myeloma (13 papers, 2012 to 2025). "Transcription factor PU.1, encoded by gene SPI1, acts as tumor suppressor for myeloma cells through direct transcriptional repression of IRF4." (PMID 35338347, 2023). "Meanwhile, abnormal hypermethylation of the SPI1 regulatory regions is frequently observed in myeloma cell lines with downregulated SPI1." (PMID 28376714, 2017).
breast carcinoma (12 papers, 2014 to 2026). "Herein, we identified ubiquitin specific peptidase 30 antisense RNA 1 (USP30-AS1) as a markedly upregulated lncRNA in breast cancer tissues, and the transcription factor SPI1 functions upstream to regulate the expression of USP30-AS1." (PMID 41492473, 2026). "A significant positive correlation between USP30-AS1 and SPI1 expression (r = 0.52) was observed in breast cancer." (PMID 41492473, 2026). "The pleiotropic variant rs71475909 was found to be associated with breast cancer risk and eosinophil counts, and this variant is in LD with a splicing QTL of SPI1 in blood cells." (PMID 38308367, 2024). "SPI1 protein levels are higher in breast cancer tissues, and high SPI1 expression is correlated with the progression of breast cancer." (PMID 37539493, 2023). "In summary, these results indicate that SPI1 may contribute to the up-regulation of USP30-AS1 in breast cancer." (PMID 41492473, 2026). "Moreover, an elevated expression of SPI1 in breast cancer was confirmed through RNA-seq data from the TCGA dataset." (PMID 41492473, 2026). "In addition, SPI1 and another proposed pleiotropic factor, ZFPM1/FOG1 (which is linked to BRCA1-associated breast cancer and eosinophil counts, among other blood traits), are involved in the lineage commitment of eosinophils." (PMID 38308367, 2024). "In breast cancer, lung cancer and cervical cancer, SPI1 plays a role in promoting cancer." (PMID 35361282, 2022). "In recent years, research has shown that SPI1 might be related to the progression of breast cancer, cervical cancer, lung cancer, glioma, and other malignant tumors." (PMID 35237521, 2022). "This may be also the case for breast cancer, as PU.1 (SPI 1) is discovered in breast cancer too (Dataset NCBI GEO Profiles, ID: 2383767, 6783968, 77599439, 77894723, 82510260)." (PMID 25329802, 2014). "The TF SPI1 and the RBPs ESRP1, ESRP2 and PCBP1 featured frequently in detected statistical interactions, suggesting additional mechanistic roles for these proteins in breast cancer." (PMID 38838009, 2024).
acute lymphoblastic leukemia (11 papers, 2006 to 2025). Leukemia with an acute onset, characterized by the presence of lymphoblasts in the bone marrow and the peripheral blood. "SPI1 fusion genes in T-cell acute lymphoblastic leukemia (T-ALL) are commonly found with co-occurring NRAS mutations." (PMID 34230493, 2021). "Spi-1 Proto-Oncogene (SPI1) fusion genes are recurrently found in T-cell acute lymphoblastic leukemia (T-ALL) cases but are insufficient to drive leukemogenesis." (PMID 34230493, 2021). "Deletion of SPI1 and the related ETS‐transcription factor SPI‐B in the B‐cell lineage results in fully‐penetrant pre‐B‐cell acute lymphoblastic leukemia (B‐ALL), suggesting that SPI1 and SPI‐B are tumor suppressors in the B‐cell lineage." (PMID 27506447, 2016).
colorectal cancer (11 papers, 2015 to 2025). A primary or metastatic malignant neoplasm that affects the colon or rectum.
autoimmune disease (10 papers, 2015 to 2025). A disorder resulting from loss of function or tissue destruction of an organ or multiple organs, arising from humoral or cellular immune responses of the individual to their own tissue constituents. "Similarly, SP1 and JUN have been shown to function together to induce TNF expression in response to viral infection and SPI1 has been shown to promote IL10 expression —a cytokine often seen to be dysregulated in autoimmune diseases as in PR3+ AAV." (PMID 36768148, 2023).